SLC12A9 (solute carrier family 12 member 9)
Description:
May be an inhibitor of SLC12A1. Seems to correspond to a subunit of a multimeric transport system and thus, additional subunits may be required for its function. May play a role in lysosomal ion flux and osmoregulation.
Synonyms: hCCC6; CCC6; CIP1; WO3.3
Tractability: Small molecule: it belongs to a druggable protein family. Antibody: UniProt places it where antibodies can reach, with high confidence; UniProt predicts a signal peptide or a membrane-spanning region; its Gene Ontology location is reachable by antibodies, with medium confidence. PROTAC: ubiquitination databases record sites on it; its protein half-life has been measured.
Gene: Protein-coding gene on chromosome 7 (100,826,820 to 100,867,017, forward strand). Ensembl gene ENSG00000146828.
Subcellular location: Cell membrane; Lysosome membrane
Gene Ontology:
Molecular function: chloride:monoatomic cation symporter activity; transmembrane transporter activity
Biological process: potassium ion transmembrane transport; chloride transmembrane transport; monoatomic ion transport; transmembrane transport
Cellular component: extracellular exosome; lysosomal membrane; apical plasma membrane; membrane; plasma membrane
Genetic constraint (gnomAD): Loss-of-function variants: 57 observed, 70.6 expected, observed/expected ratio (o/e) 0.81, 90% interval 0.65 to 1.01. The upper end of that interval is the gene's LOEUF score, 1.01, which puts it in group 4 of 6, group 1 being the genes least tolerant of losing a copy. Missense variants: 1,061 observed, 1,252.1 expected, observed/expected ratio (o/e) 0.85, 90% interval 0.81 to 0.89. Synonymous variants: 576 observed, 569.74 expected, observed/expected ratio (o/e) 1.01, 90% interval 0.94 to 1.08.
Homologues: Orthologues: chimpanzee SLC12A9 (99% identical), macaque SLC12A9 (99% identical), pig SLC12A9 (95% identical), guinea pig SLC12A9 (94% identical), rabbit SLC12A9 (94% identical), rat Slc12a9 (94% identical), dog SLC12A9 (93% identical), mouse Slc12a9 (93% identical), tropical clawed frog slc12a9 (62% identical), zebrafish slc12a9 (57% identical), Drosophila melanogaster CG10413 (41% identical), Caenorhabditis elegans T04B8.5 (39% identical). Paralogues in human: SLC12A6 (29% identical), SLC12A4 (29% identical), SLC12A7 (28% identical), SLC12A5 (28% identical), SLC12A1 (26% identical), SLC12A2 (26% identical), SLC12A3 (24% identical), SLC12A8 (15% identical).
Diseases named in the same sentence as SLC12A9 in open-access papers:
SLC12A9 is named in the same sentence as 10 diseases in open-access papers, as found by Europe PMC text mining. Sharing a sentence is not in itself a finding about the gene and the disease. The quoted sentences say what the papers report.
melanoma (2 papers, 2021 to 2023). A malignant, usually aggressive tumor composed of atypical, neoplastic melanocytes. "To validate the results at the protein level, we performed immunohistochemistry of TRIB3 and SLC12A9 (risk genes) in metastatic and primary melanoma tissues." (PMID 37268878, 2023). "The gene-signature contained three genes, including TRIB3, TMEM101, and SLC12A9, of which some have been reported to be correlated to melanoma and other tumors." (PMID 37268878, 2023). "Both SLC12A9 and SLC45A2, which we associate with melanoma and non-melanoma skin cancer, are implicated with pigmentation according to the Open Targets Platform62." (PMID 34290314, 2021).
uveal melanoma (2 papers, 2023 to 2025). A melanoma derived from melanocytes of the uveal tract. "Upregulated solute carrier SLC12A9 is associated with aggressive uveal melanoma, while PYCARD encodes an apoptosis-inducing factor and is characteristically suppressed by hypermethylation in aggressive PCa." (PMID 41057544, 2025).
colon cancer (1 paper, 2023). "The results demonstrated a significant upregulation of SLC12A9 expression in colon cancer compared to the paired normal tissue samples (*p < 0.05)." (PMID 38157260, 2023).
colorectal cancer (1 paper, 2023). A primary or metastatic malignant neoplasm that affects the colon or rectum. "The study further investigated the diagnostic potential of SLC12A9 in colorectal cancer." (PMID 38157260, 2023). "This study aimed to explore the involvement of SLC12A9 in colorectal cancer (CRC) through multiple analysis techniques, including expression analysis and prognostic evaluation." (PMID 38157260, 2023). "In order to analyze SLC12A9, the mean (Mean) and standard deviation (SD) were computed for both colorectal cancer and normal tissue samples." (PMID 38157260, 2023). "At present, some studies have preliminarily shown that SLC12A9 plays a key role in colorectal cancer." (PMID 38157260, 2023). "However, no bioinformatics studies have explored the role of SLC12A9 in colorectal cancer in depth." (PMID 38157260, 2023).
Insulin resistance (1 paper, 2017). Increased resistance towards insulin, that is, diminished effectiveness of insulin in reducing blood glucose levels. "Three genes, SLC12A9 (chromosome 12), CACNA1D and CSMD1 (chromosome 16), were associated with both blood pressure and insulin resistance-related metabolic traits." (PMID 28130354, 2017).
metastatic melanoma (1 paper, 2023). A melanoma that has spread from its primary site to another anatomic site. "Compared to primary samples, the proteins of TRIB3 and SLC12A9 were highly expressed in metastatic melanoma." (PMID 37268878, 2023).
tumor (2 papers, 2023 to 2025). "In the initial phase of this study, the expression of SLC12A9 was examined in tumor and normal tissues within each data set." (PMID 38157260, 2023). "While PYCARD (cg11970458), but not SLC12A9 (cg04742719), exhibits a role in PCa, the observed tumour versus normal hypermethylation of these particular CpGs appears to be African-specific." (PMID 41057544, 2025).
SLC12A9 also shares sentences with these, for which no sentence is quoted: dyslipidemia (1 paper); Esophageal Carcinoma (1); non-melanoma skin carcinoma (1).